MPO (myeloperoxidase)
Diseases named in the same sentence as MPO in open-access papers (continued):
Sharing a sentence is not in itself a finding about the gene and the disease.
Stroke (continued). "Concordant with MPO immunostaining results, the amount of MPO protein was higher in the aged brain as compared to that of the young adult on day 10 after stroke (p = 0.0159 and p = 0.0317 respectively)." (PMID 39325942, 2024). "We next investigated the impact of 4-aminobenzoic acid hydrazide (ABAH), an irreversible and specific MPO inhibitor, on neurobehavior outcomes during the early subacute stage following stroke in aged mice." (PMID 39325942, 2024). "Stroke Homing peptide (SHp)-guided deoxyribonuclease 1 (DNase1) and inhibition of myeloperoxidase (MPO) or peptidyl arginine deiminase-4 (PAD4) can reduce chemotherapy-induced mechanical hyperalgesia and prevent the development of CIPN in mice model." (PMID 39202733, 2024). "As expected, MPO tissue imaging on day 3 after stroke revealed decreased MAFA signals in ABAH-treated brains compared to those in untreated brains (p = 0.0159)." (PMID 39325942, 2024). "In contrast, in the blood, a higher percentage of MPO+ cells were found in aged mice as compared to those of young adult mice on day 3 after stroke (p = 0.0286)." (PMID 39325942, 2024). "Conversely, a decreased percentage of MPO+ cells was observed in the blood of aged mice compared to young adult mice on day 10 after stroke (p = 0.0317)." (PMID 39325942, 2024). "In this study, we developed and utilized the new MAFA agent to track MPO activity on ischemic tissues longitudinally in aged and young adult mice after stroke." (PMID 39325942, 2024). "Although both groups experienced a decline in the percentage of MPO+ infiltrating Mφ/activated Mg on day 10 after stroke, the levels remained elevated in the brains of aged mice compared to young adult mice (p = 0.0079)." (PMID 39325942, 2024). "MAFA imaging revealed that aged brains have markedly higher MPO activity that increased after stroke on day 3 compared to young adult brains." (PMID 39325942, 2024). "For time-to-event analysis, MPO-DNA, Caspase-1 and IL-1β at baseline were predictors of MVEs after stroke (HR:4.04 (95%CI 1.28-12.70), 2.33 (95%CI 1.06-5.12) and 4.09 (95%CI 1.39-11.99), respectively)." (PMID 39737165, 2024). "Elevated plasma levels of MPO-DNA and citH3 after stroke onset have shown positive correlations with stroke outcomes." (PMID 39606238, 2024). "Although MPO activity decreased markedly in both aged and young adult mice by day 10 after stroke, it remained elevated in the aged brains compared to the young adult brains." (PMID 39325942, 2024). "Together these results revealed that young adults are more resilient toward inflammatory damage after ischemic stroke, with less secreted MPO during the early subacute phase of stroke and a faster resolution as stroke evolved." (PMID 39325942, 2024). "Other authors have also proven the ability of trigonelline to interact with myeloperoxidase (MPO; a well-known stroke-related inflammation protein), blocking its action and protecting the brain from MPO-mediated inflammation after stroke." (PMID 39000542, 2024). "On day 10 post-stroke, a further elevation in the percentage of MPO+ cells was evident in the brains of aged mice compared to young mice (p = 0.0317)." (PMID 39325942, 2024). "Stroke, attributed to vascular disease, was induced by MPO by destroying the integrity of blood vessels, either directly or indirectly." (PMID 38275657, 2024). "Since we demonstrated that aging affected immune cell recruitment and altered neurological outcomes after stroke, we next investigated how MPO activity changes in aged and young adult brains on days 3 and 10 after stroke using MAFA." (PMID 39325942, 2024). "Neutrophil-derived MPO activity reaches peak levels on days 1-3 after a stroke, while macrophage/microglia-derived MPO activity peaks on days 5-7." (PMID 37266435, 2023). "N-acetyl lysyltyrosylcysteine amide (KYC), an MPO-specific inhibitor, has been shown to effectively reduce oxidative stress-mediated brain injury after stroke by reducing 4-HNE and other toxic oxidants in vivo." (PMID 36768969, 2023).
Stroke (continued). "In a prospective study on patients with symptomatic PAD, MPO levels ≥ 183.7 pM were predictive of myocardial infarction or stroke during a median follow-up of 17.5 months." (PMID 36674682, 2023). "Elevated MPO levels are associated with inflammation and oxidative stress and are predictive of CVD risk, including thrombosis and stroke." (PMID 37475160, 2023). "4-aminobenzoic acid hydrazide (ABAH), an irreversible specific MPO inhibitor, has been found to improve multiple sclerosis (MS) and stroke in experimental models." (PMID 36892020, 2023). "In a mouse model of stroke, we previously found that acute hyperglycemia led to an increase in the cerebral level of myeloperoxidase, used as an indicator of neutrophil recruitment." (PMID 35624723, 2022). "Both plasma H3cit and MPO-DNA levels positively correlated with stroke outcomes (r = 0.45, P = 0.024, and r = 0.507, P = 0.01, respectively)." (PMID 35358095, 2022). "Our finding that early MPO genetic scores are predictive of CAD and stroke risk must be tempered by the complex genetic architecture of myeloperoxidase levels." (PMID 35504531, 2022). "MPO has been shown to correlate with infarct size, stroke severity and mortality and can be detected up to 3 weeks post infarct." (PMID 35042473, 2022). "The presence of neutrophils (MPO+ cells) and NETs (CitH3+) was recently evaluated in cerebral thrombi of different stroke etiology, i.e., cardioembolic, large artery atherosclerosis, or undetermined cause, retrieved by endovascular thrombectomy." (PMID 35844591, 2022). "Using this model, we observed a significant increase in circulating levels of HMGB1 and MPO-DNA complexes 6 and 24 hours after stroke in comparison with sham animals, consistent with our observations in human ischemic stroke patients." (PMID 35358095, 2022). "This tripeptide inhibitor of MPO has been shown to limit neuronal damage and inflammation in murine models of stroke and protects bovine aortic endothelial cells from MPO-mediated damage." (PMID 36293108, 2022). "In study population B, higher levels of MPO and Anti-Apo A1 were noted in patients with a previous stroke." (PMID 35042473, 2022). "More research will be required to unambiguously pinpoint myeloperoxidase as a therapeutic target in stroke and coronary artery disease." (PMID 35504531, 2022). "Reversible inhibitors of MPO include the small peptide N-acetyl lysyltyrosylcysteine amide, which has anti-tumorigenic effects and reduces inflammation in models of stroke and endothelial inflammation." (PMID 36293108, 2022). "In blood samples at the hyper-acute phase of stroke and 7 days later, we determined cell-free DNA, myeloperoxidase-histone complexes, DNase activity, myeloperoxidase activity, LL-37 and inflammatory cytokines." (PMID 35619694, 2022). "The CytoHubba plug-in of the Cytoscape was utilized to visualize the genes of stroke-related crucial module, and the top five genes were selected as hub genes using EcCentricity as the ranking method (MPO, MMP9, ITGA2B, ITGB3, and RETN)." (PMID 35557984, 2022). "Inhibition of MPO by N-acetyl lysyltyrosylcysteine amide significantly decreases IgG extravasation and neurological severity score in stroke." (PMID 34248961, 2021). "Higher neutrophil counts and myeloperoxidase (MPO) plasma concentration in plasma were positively correlated with stroke severity and worsened outcomes." (PMID 34248961, 2021). "When oxidative enzyme myeloperoxidase (MPO) activity was inhibited after stroke, there was a noticeable reduction in the number of M1 microglial cells, but there was no impact on M2 microglia." (PMID 34944064, 2021). "We then found a marked 5.3-fold increase in total content of the neutrophil enzyme MPO in the cortical areas at 3 days after stroke." (PMID 32427863, 2020). "MPO activity derived from neutrophils was peaked at day 1–3 of stroke onset, whereas MPO from the macrophage/microglia at day 5–7." (PMID 32508671, 2020).
Stroke (continued). "The increased MPO activity was reported in both experimental stroke animal models and ischemic stroke patients." (PMID 32508671, 2020). "As markers and mediators of systemic inflammation, increases in inflammatory cytokines, such as interleukin (IL)-2, IL-6, myeloperoxidase, and integrins, are abundant in polymorphonuclear neutrophils and are related to oxidative stress after a stroke." (PMID 32231119, 2020). "In the clinical setting, we previously showed that the circulating levels of neutrophil degranulation products (MMP-8, MMP-9, MPO and NE) peak in stroke patients receiving r-tPA during the first hour after drug administration." (PMID 32977685, 2020). "In the present study, 4 weeks of ET enhanced platelet mitochondrial OXPHOS and ETC capacities by increasing Complex II activity, but lowered plasma MPO and IL-6 concentrations in the stroke patients." (PMID 31835774, 2019). "The present investigation demonstrated that moderate-intensity ET significantly decreased plasma MPO and IL-6 levels, inflammatory cytokines, in stroke patients." (PMID 31835774, 2019). "The increasing MPO level and MPO/HDL-C, MPO/apoAI ratios can differentiate the SCAD patients at the risk of acute coronary syndrome (ACAD) and stroke." (PMID 29618370, 2018). "In line with deleterious effects of MPO-generated 2-ClHDA, the MPO inhibitor N-acetyl lysyltyrosylcysteine amide ameliorates brain damage in a murine model of stroke and counteracts BBB damage in a murine model of MS." (PMID 29413957, 2018). "The increasing MPO level and MPO/HDL-C, MPO/apoAI ratios can differentiate the SCAD of patients at the risk of acute coronary syndrome (ACAD) and stroke." (PMID 29618370, 2018). "Here, we investigated the intra- and extracellular levels of two key enzymes, MPO and NE, that are involved in NETosis and the oxidative burst post-stroke." (PMID 28732504, 2017). "On day 1 post-stroke intracellular MPO was significantly reduced in stroke patients’ granulocytes compared to controls (MPO–MFId1(mean ± SD): 4598 ± 1642 vs. MPO–MFIControl: 6580 ± 1955; p = 0.0136)." (PMID 28732504, 2017). "MPO was measured on the day of stroke admission (d0) and on days 1, 3 and 5 after stroke (d1, d3, d5) (A; ncrtl = 14, nd0 = 14, nd1 = 18, nd3 = 14, nd5 = 16)." (PMID 28732504, 2017). "MPO was reduced in granulocytes but increased in sera obtained from stroke patients compared to controls." (PMID 28732504, 2017). "In experimental stroke models, brain damage was also ameliorated by inhibiting myeloperoxidase oxidant (MPO) production, with N-acetyl lysyltyrosylcysteine amide or with the flavonoid, eriodictyol." (PMID 28331857, 2017). "The impact of enhanced MPO and NE serum levels in stroke patients should be addressed in future studies." (PMID 28732504, 2017). "In stroke patients, intracellular MPO was reduced in granulocytes, and a similar finding was also observed in monocytes." (PMID 28732504, 2017). "To identify the factors that trigger MPO and NE modulation in stroke, we investigated the role of catecholamines, dexamethasone and acetylcholine." (PMID 28732504, 2017). "Because the autonomous nervous system is thought to mediate stroke-induced immune alterations, we also studied the influence of stress hormones and acetylcholine on MPO and NE." (PMID 28732504, 2017). "Taken together, these reports provide strong evidence for direct links between MPO activity and severity of brain injury in stroke, providing the rationale for inhibiting MPO activity as a novel therapeutic strategy for stroke." (PMID 27220420, 2016). "Until recently, the role of myeloperoxidase (MPO) in stroke has been limited to serving as a biomarker for neutrophil infiltration." (PMID 27220420, 2016). "In the present study, we investigate if KYC reduces brain injury in MCAO mice and the extent to which MPO-dependent oxidative stress mediates brain injury and cell death after stroke." (PMID 27220420, 2016).
Stroke (continued). "T1 shortening in neuroinflammation areas using this molecule has been proved to be specific by its negativity in a MPO-knockout stroke mice." (PMID 26705534, 2015). "MPO-Gd has been used to assess neuroinflammation in stroke and EAE, as well as to detect neuroinflammation following treatment by oncolytic virus in a rat model of glioma." (PMID 26705534, 2015). "The stroke-induced MPO and LCN2 was minimally detected in the pMCAO model and significantly lower than the tMCAO model, showing that the infiltration of immune cells in pMCAO was not as pronounced as in tMCAO." (PMID 25702801, 2015). "MPO-specific signal peaked on day 3 after stroke, which was confirmed using in vitro MPO activity and RT-PCR assays." (PMID 25525560, 2014). "In the MCAO mouse model of stroke, MPO-Gd enhanced MR imaging detected widespread secretion of MPO into the ischemic areas, and MPO-Gd positive lesion volume correlated well with infarct size." (PMID 25525560, 2014). "Comparable findings of MPO release from neutrophils and macrophages/microglia were reported in a mouse model of stroke." (PMID 23691142, 2013). "Enzyme myeloperoxidase (MPO) is another emerging biomarker and elevated MPO levels have been found in stroke patients and in eroded or ruptured plaques that have caused acute coronary syndromes." (PMID 24232739, 2013). "Consequently, MPO has emerged as a viable therapeutic target for reducing secondary brain damage and a potential biomarker for determining the severity of a stroke." (PMID 41373489, 2025). "MPO, a pro-inflammatory enzyme secreted in large quantities by activated myeloid cells following stroke, plays a critical role in the pathogenesis of both hemorrhagic and ischemic strokes, contributing to blood-brain barrier (BBB) disruption and subsequent brain injury." (PMID 40777988, 2025). "MPO, a product of neutrophil-mediated inflammatory responses, has been extensively documented to participate in the pathogenesis of various diseases including coronary atherosclerosis, stroke, neurodegenerative disorders, and malignancies." (PMID 41451132, 2025). "Finally, immunofluorescence staining showed a higher positivity rate for Ly6G (neutrophil marker) and MPO in the stroke group compared to the sham group, while the positivity rate was decreased in the stroke+CI group." (PMID 41098728, 2025). "Additionally, we found an increased percentage of MPO+ cells in the blood of aged mice following stroke during the early subacute phase, highlighting an age-related amplification of the bone marrow response." (PMID 39325942, 2024). "Unraveling the relationship between aging, MPO activity, and stroke outcomes could allow more rational design of more effective therapeutic interventions that benefit different age groups after stroke." (PMID 39325942, 2024). "Myeloperoxidase (MPO) plays an important role in stroke-related inflammation." (PMID 38542359, 2024). "We observed that the administration of ABAH, a specific irreversible MPO inhibitor, mitigated the inflammatory response, reduced MPO activity, and improved neurobehavioral scores, contributing to a significant improvement in survival rates by day 3 after stroke in the aged group." (PMID 39325942, 2024). "However, markers indicative of NET formation, such as H3cit and MPO-DNA levels, exhibit a positive correlation with stroke outcomes." (PMID 38654328, 2024). "Notably, most deaths in the aged occurred within the first few days after stroke, which is likely related to the markedly elevated MPO activity we observed between days 0 (naïve) to day 3 in the aged group." (PMID 39325942, 2024). "Interestingly, double immunofluorescent staining of MPO protein and MAFA showed that aged brains have less MPO protein compared to those of young adult brains on day 3 after stroke (p = 0.0286)." (PMID 39325942, 2024). "Myeloperoxidase participate in the occurrence and development of stroke." (PMID 36901834, 2023).
Stroke (continued). "In summary, MPO inhibition is a potentially promising therapeutic strategy for stroke." (PMID 36892020, 2023). "The inhibition of myeloperoxidase, a pro-inflammatory enzyme mainly secreted by myeloid cells after stroke in the central nervous system, decreases the inflammatory progress in the brain and improves clinical outcome, as found by John Chen and his colleagues in animal models." (PMID 37998540, 2023). "Myeloperoxidase can participate in the onset and exacerbation of stroke-induced damage." (PMID 36901834, 2023). "Additionally, plasma levels of PF4 correlated with both plasma H3cit and MPO-DNA levels in our cohort (r = 0.376, P = 0.024, and r = 0.556, P = 0.001, respectively), implying a role for platelet activation in stroke-induced NET formation." (PMID 35358095, 2022). "Notably, as in brain tissue, all MPO+ cells also stained for NE in stroke patient thrombi, implying that MPO in thrombi and brain tissue is mainly of neutrophil origin." (PMID 35358095, 2022). "Moreover, in EAE and stroke mouse models, inhibition of MPO with N-acetyl lysyltyrosylcysteine amide prevented BBB breakdown and reduced disease severity, further demonstrating a role for MPO in CNS barrier breakdown." (PMID 36034148, 2022). "If damage has already occurred, such as in myocardial infarction and stroke, a targeted MPO inhibitor approach could be therapeutically useful to prevent further damage from the MPO-induced inflammatory responses." (PMID 35326206, 2022). "MPO could prove a useful biomarker in relation to CKD and stroke risk and in relation to outcomes of stroke in patients with CKD." (PMID 35042473, 2022). "Myeloperoxidase (MPO) activity and inflammatory proteins (nuclear factor kappa-B (NF-κB), inducible nitric oxide synthase (iNOS)) in the small intestine were significantly increased in mice after stroke." (PMID 33642941, 2021). "The expression of MPO of the stroke 1-day group was higher than that of the sham 1-day group (n = 7, p < 0.001), and the level in the stroke 7-day group was higher than that in the control group while lower than that in the stroke 1-day group (n = 7, p < 0.01)." (PMID 33642941, 2021). "Increased serum MPO values were also observed in patients with stroke." (PMID 34821692, 2021). "The upregulation of iNOS and MPO reflects the increase in intestinal oxidative stress after stroke." (PMID 33642941, 2021). "In stroke patients, MPO expression is increased in both the plasma and the serum." (PMID 33573686, 2021). "On the murine models, increased MPO values persisted for 21 days after stroke." (PMID 34821692, 2021). "Stroke patients present higher MPO expression in both plasma and serum." (PMID 33535986, 2021). "MPO-positive cells were significantly increased in the brains of tPA-treated stroke mice." (PMID 35095486, 2021). "Therefore, MPO exerts its roles in mediating oxidative stress and inflammation and affects adult neurogenesis in the post-stroke brain." (PMID 32508671, 2020). "Therefore, in the present study, we assessed neuroprotective effects of intra-arterially administered tacrolimus as kind of an anti-inflammatory model substance in a murine stroke model, utilizing 7 T MR imaging with a MPO-sensitive contrast agent." (PMID 29335483, 2018). "The rapid increase in systemic inflammation may cause an increase in MPO concentration which may cause ACS and stroke in patients who had low lipid and lipoprotein at the beginning of studies." (PMID 29618370, 2018). "Intra-arterially administered anti-inflammatory agents after mechanical thrombectomy may improve treatment efficiency in stroke by reducing infarct volume size and MPO activity." (PMID 29335483, 2018). "To explain the reduced respiratory burst and impaired NETosis after stroke, we analysed the intracellular amounts of MPO and NE in patients’ granulocytes and monocytes and compared the results to those obtained with cells from age- and sex-matched healthy subjects." (PMID 28732504, 2017).